LINC01871 (long independently transcribed non-coding RNA 1871)
Gene: Long non-coding RNA gene on chromosome 2 (7,720,139 to 7,749,426, forward strand). Ensembl gene ENSG00000235576.
Diseases named in the same sentence as LINC01871 in open-access papers:
LINC01871 is named in the same sentence as 9 diseases in open-access papers, as found by Europe PMC text mining. Sharing a sentence is not in itself a finding about the gene and the disease. The quoted sentences say what the papers report.
breast carcinoma (9 papers, 2020 to 2023). "Studies have demonstrated that LINC01871 is involved in stemness, autophagy, ferroptosis, and the immune microenvironment in breast cancer cells; it was reported to be associated with a good prognosis and a lower incidence of distant metastasis in gastric, cervical, and endometrial cancers." (PMID 38083905, 2023). "According to a recent review of the literature, LINC01871 has been identified by several studies in breast cancer through bioinformatic measurement involving the cellular phenotype of autophagy, stemness, immune response, ferroptosis, and lipid metabolism." (PMID 36338982, 2022). "The predicting value of 11 sARLNRs (U62317.4, LINC01016, LINC02166, C6orf99, LINC00992, BAIAP2-DT, AC245297.3, AC090912.1, Z68871.1, LINC00578, and LINC01871) was also identified in breast cancer." (PMID 34414116, 2021). "In conclusion, we identified a novel autophagy‐related prognostic risk model consisting of 11 lncRNAs (U62317.4, LINC01016, LINC02166, C6orf99, LINC00992, BAIAP2‐DT, AC245297.3, AC090912.1, Z68871.1, LINC00578 and LINC01871) in breast cancer." (PMID 33216456, 2021). "The heatmap also showed that MAPT‐AS1, LINC01871, AL122010.1, AC090912.1, AC061992.1 were up‐regulated in low‐risk breast cancer." (PMID 33694315, 2021). "Except for AL161646.1 and LINC00578 (p < 0.0001), lncRNAs, including OTUD6B-AS1, AC245297.3, AC136475.2, AL122010.1, AL161646.1 and LINC01871, were high expressed between breast cancers and normal tissues." (PMID 33225954, 2020). "This suggests that LINC01871 may play a protective role in breast cancer." (PMID 36338982, 2022). "We can speculate that LINC01871 may be a protective factor in breast cancer." (PMID 33694315, 2021).
cervical cancer (2 papers, 2020 to 2025). A primary or metastatic malignant neoplasm involving the cervix. "Of these five autophagy-related lncRNAs, the functions of LINC01871, SOS1-IT1, and AL161618.1 are not clear; however, SCARNA9 is downregulated in cervical cancer." (PMID 33381557, 2020).
gastric cancer (2 papers, 2021 to 2023). A primary or metastatic malignant neoplasm involving the stomach. "LINC01871 is involved in the construction of an immune prognostic model of gastric cancer." (PMID 33694315, 2021).
autoimmune disease (1 paper, 2022). A disorder resulting from loss of function or tissue destruction of an organ or multiple organs, arising from humoral or cellular immune responses of the individual to their own tissue constituents. "The upregulation of LINC01871 might indicate a dysregulation of T cell inflammatory responses in UC as has been reported for several other autoimmune diseases." (PMID 35224318, 2022).
COVID-19 (1 paper, 2021). A disease caused by infection with severe acute respiratory syndrome coronavirus 2. "It has been observed that increased level of LINC02207, LINC01127 was associated with the severe COVID-19 group, whereas LINC02084, LINC02446, LINC00861, LINC01871, and ANKRD44-AS1 were associated with the mild COVID-19 group." (PMID 34940755, 2021).
tumor (5 papers, 2021 to 2025). "LINC01871 is an established protective factor in BC and is associated with autophagy, ferroptosis, and tumor stem cells." (PMID 35528236, 2022). "Tumors in the sh‐LINC01871 group were significantly smaller in size and lighter in weight compared to those in the sh‐NC group, demonstrating that LINC01871 knockdown inhibited HeLa cell‐derived tumor growth in vivo." (PMID 40035259, 2025). "Furthermore, animal experiments revealed that LINC01871 silencing inhibited tumor growth derived from HeLa cells in a xenograft mouse model, further confirming the oncogenic role of LINC01871 in CC." (PMID 40035259, 2025). "Consistent with the in vitro findings, animal experiments showed that LINC01871 knockdown downregulated MAP3K2 protein expression and suppressed the phosphorylation of ERK, JNK, and p38 in tumor‐bearing mice." (PMID 40035259, 2025). "LINC01871 knockdown significantly suppressed CC cell invasion, migration, EMT, and immune escape in vitro and reduced tumor growth in vivo." (PMID 40035259, 2025). "Moreover, LICN01871 silencing suppressed the expression of LINC01871 and MAP3K2 while upregulating miR‐873‐3p levels in tumor tissues." (PMID 40035259, 2025). "Nevertheless, the specific functions of ELN-AS1, AC103563.7, AF131215.5, LINC01871, AC08417.1, NRAV, AL049539.1, POC1B-AS1, AC108134.4, and AC019080.5 in the tumor microenvironment remain unknown." (PMID 34925511, 2021). "The LINC01871/miR‐4644 and miR‐185‐5p/GNLY axes might affect distant metastasis and prognosis (DFS) of CRC by regulating the radiosensitivity, ferroptosis, autophagy, and stemness of CRC cells and the tumor immune microenvironment." (PMID 38083905, 2023).
cancer (3 papers, 2021 to 2022). A tumor composed of atypical neoplastic, often pleomorphic cells that invade other tissues. "To date, the role of 5 lncRNAs in our model, including AC004585.1, DLGAP1‐AS1, TNFRSF14‐AS1, Z68871.1 and LINC01871, has been studied in BC and other cancers." (PMID 34632690, 2021). "This was consistent with our findings, which led us to hypothesize that the NRGs co-expressed with LINC01871 may promote cancer cell death by necroptosis." (PMID 35528236, 2022). "For LINC01871, many studies have confirmed that it may be a protective factor of BC, promoting cancer cells death through many pathways and mechanisms, such as autophagy, which is consistent with our study results." (PMID 34671639, 2021).
LINC01871 also shares sentences with these, for which no sentence is quoted: colorectal adenocarcinoma (1 paper); endometrial cancer (1).